HMGB1 (high mobility group box 1)
Diseases named in the same sentence as HMGB1 in open-access papers (continued):
Sharing a sentence is not in itself a finding about the gene and the disease.
Insulin resistance (continued). "When insulin resistance is present, the expression of proteins named high-mobility group box-1 (HMGB1) and receptor for advanced glycation end-products (RAGE) is elevated, resulting in the subsequent activation of toll-like receptor 4 (TLR4)." (PMID 37511207, 2023). "HMGB1 accelerates insulin resistance by increasing the expression of RAGE, activating the TLR4/JNK/NF-κB pathway and reducing activation of the IRS-1 signaling pathway." (PMID 37065747, 2023). "Increased HMGB1 can increase TLR4 and RAGE, enhance the activity of the autophagy signaling pathway, and lead to dysregulated autophagy, thus causing insulin resistance, systemic inflammatory response, and organ dysfunction." (PMID 37065747, 2023). "Research has shown that inhibition of HMGB1 or the TLR4/NF-κB signaling pathway can improve inflammatory PCOS with insulin resistance." (PMID 37691930, 2023). "Recent data suggest that HMGB1 acts as an adipokine in metabolic syndrome and plays a central role in the pathogenesis of insulin resistance." (PMID 35834066, 2022). "High levels of HMGB1 have been observed in diabetics with diabetic nephropathies and retinopathy and insulin resistance." (PMID 33114431, 2020). "Collectively, these results indicate that FBXW7 ameliorates hepatic inflammation and consequent insulin resistance by suppressing the expression and release of HMGB1 in the HFD-fed mice." (PMID 31215394, 2019). "Taken together, these results suggest that inhibition of HMGB1 can reduce retinal insulin resistance, as well as protect the retina against I/R-induced damage." (PMID 28542588, 2017). "One potential upstream regulator of TNFα and insulin resistance is high mobility group box 1 (HMGB1)." (PMID 28542588, 2017). "In a number of human studies with obese state or T2D, circulating level of HMGB1 was higher and positively correlated with homeostasis model assessment-insulin resistance (HOMA-IR)." (PMID 28101517, 2016). "The current study is aimed to investigate the relationship of plasma HMGB1 levels with body fat, glycolipid metabolism, insulin resistance (IR) and inflammation in obese adults and newly diagnosed T2DM patients." (PMID 26317615, 2015). "The therapeutic potentials of HMGB1 inhibitors should now be tested in the context of insulin resistance pathologies and experiments along these lines are now highly warranted." (PMID 24073286, 2013). "Elevated levels of HMGB1 and its receptors, RAGE and TLR4 proteins, were found in the lung tissue of smoking COPD patients, and CS-induced HMGB1 secretion may lead to insulin resistance." (PMID 40216765, 2025). "In addition, insulin resistance was also suggested from the elevated high mobility group box 1 (HMGB1) results in the development of insulin resistance in granulosa cells of PCOS subjects." (PMID 39859066, 2025). "Primary aim of this study was to assess whether HMGB1 serum concentrations are associated with PCOS and with the state of insulin resistance of these women." (PMID 37256493, 2023). "Taohong Siwu Decoction is composed of Persicae Semen, Angelicae Sinensis Radix, Carthami Flos, Chuanxiong Rhizoma, Rehmanniae Radix Praeparata and Paeoniae Radix Alba, which can reduce the level of HMGB1, alleviate insulin resistance and reduce inflammation in T2DM patients." (PMID 37065747, 2023). "Thus, this study provided experimental evidence that FBXW7 ameliorated hepatic inflammation and insulin resistance by suppressing the expression and release of HMGB1 in NAFLD." (PMID 31215394, 2019). "Our results demonstrate a protective role of FBXW7 in NAFLD by abating HMGB1-mediated innate immune signaling to suppress inflammation and consequent insulin resistance, suggesting that FBXW7 is a potential target for therapeutic intervention in NAFLD development." (PMID 31215394, 2019).
Insulin resistance (continued). "In this study, we hypothesized that FBXW7 ameliorates the development and progression of NAFLD through abating HMGB1-mediated innate immune signaling to suppress inflammation and consequent insulin resistance." (PMID 31215394, 2019). "Interestingly, HMGB1 is also involved in DM initiation, altering insulin secretion and insulin resistance." (PMID 31835864, 2019). "It is crucial to note that HMGB-1 may induce islet cells apoptosis and insulin resistance via binding to TLR4 and then contribute to initiation and development of DM." (PMID 27847406, 2016). "Activation of TLR4, another receptor of HMGB-1, activated proinflammatory kinases (such as p38MAPK and JNK) that impaired insulin signal transduction via inhibitory phosphorylation of insulin receptor substrate, suggesting the involvement of HMGB-1 in insulin resistance." (PMID 27847406, 2016). "The presence of macrophages with potent pro-inflammatory activities and in response to HMGB1 released in the vicinity of the adipocytes may contribute further to insulin resistance." (PMID 24073286, 2013). "The role of HMGB1 on macrophages is clearly described and stimulation of macrophages with HMGB1 induces a production of pro-inflammatory cytokines which can lead to an increase of adipose tissue inflammation and insulin resistance." (PMID 24073286, 2013). "Hence, this relation between IL6 and insulin resistance should be extended to propose a central role of HMGB1 in insulin resistance through it action on IL6 secretion." (PMID 24073286, 2013). "Unfortunately, these authors did not use a multivariable analysis to verify whether the association between serum testosterone and HMGB1 levels was independent of insulin resistance." (PMID 37256493, 2023). "In addition, it has been reported that serum HMGB1 levels are positively correlated with FINS and HOMA-IR and negatively correlated with HOMA-β, suggesting that HMGB1 may impair β pancreatic cell function and increase insulin resistance." (PMID 37065747, 2023). "Moreover, the evidence suggests this may be due to HMGB1-induced ceramide biosynthesis accrual in muscle, which provides an additional context to ceramide-induced insulin resistance." (PMID 28531105, 2017). "The role of HMGB1 on macrophages has been clearly described and stimulation of macrophages with HMGB1 induced production of proinflammatory cytokines which may lead to an increase of adipose tissue inflammation and insulin resistance." (PMID 28101517, 2016). "This suggested that HMGB1 might play a critical role in insulin resistance through NF-κB signaling." (PMID 28101517, 2016). "Insulin resistance (HOMA-IR, QUICKI), HOMA-β and elevations in plasma inflammatory cytokine levels (TNF-α, IL-6 and HMGB-1) were all attenuated by galantamine." (PMID 37731032, 2023). "In adipose cells derived from obese T2DM patients with increased levels of insulin resistance and T2DM, HMGB1 expression is mainly cytoplasmatic and secretion is raised." (PMID 34360753, 2021). "We revealed that FBXW7 effectively abated the expression and release of HMGB1, thereby suppressing TLR4 and RAGE signaling to attenuate inflammation and consequent insulin resistance, ultimately ameliorating NAFLD." (PMID 31215394, 2019). "HMGB1, as RAGE ligand, may promote insulin resistance of the brain through activating the TLR4-JNK signaling pathway, as well as through stimulating the TNF-α dependent signaling pathway." (PMID 37373216, 2023). "As a molecule associated with several inflammatory diseases, HMGB1 is elevated in both the peripheral blood and follicular fluid of women with PCOS, particularly those with insulin resistance, compared with non-PCOS women." (PMID 37691930, 2023). "In addition, in order to promoting insulin resistance in type 2 diabetic patients, Fetuin-A can also prevent the change of RAGE ligand with (HMGB1), which is responsible the release and absorption of several cytokines, adhesive molecules, and cheomokines." (PMID 33546744, 2021).
Insulin resistance (continued). "Moreover, Exogenous HMGB1 treatment abolished FBXW7-mediated inhibition of hepatic inflammation and insulin resistance in HFD-fed mouse livers." (PMID 31215394, 2019). "In addition, exogenous HMGB1 treatment abolished FBXW7-mediated inhibition of hepatic inflammation and insulin resistance in HFD-fed mouse livers." (PMID 31215394, 2019). "Nevertheless, recent data showed that increased HMGB1 may impair insulin signaling in granulosa cells obtained from PCOS patients, suggesting that both directions in the relationship between HMGB1 and insulin resistance are potentially working." (PMID 37256493, 2023). "Secondly, through promoting brain-insulin resistance with its detrimental effects on cognitive functions, Thirdly, through inducing the excessive production of some substances, such as AGE and HMGB1, which may promote neuroinflammation, thus abrogating the function of microglia and Aβ clearance." (PMID 37373216, 2023). "In addition to promoting insulin resistance in type II diabetic patients, fetuin-A can also inhibit an alternate RAGE ligand, high mobility group box-1 (HMGB1), which is responsible for the release and recruitment of several cytokines, adhesion molecules, and chemokines." (PMID 27547766, 2016). "The present data suggest that serum HMGB1 is unaffected by the PCOS status per se, and it can be hypothesized that previous findings in the comparison between PCOS women and healthy controls may indeed reflect the differences in the expected frequency of insulin resistance between the two groups." (PMID 37256493, 2023).
myocardial ischemia (43 papers, 2011 to 2025). A disorder of cardiac function caused by insufficient blood flow to the muscle tissue of the heart. "Following myocardial ischemia or endothelial injury, damage-associated molecular patterns (DAMPs), such as high-mobility group box 1 (HMGB1) and ATP, activate macrophages and neutrophils via Toll-like receptors (TLRs) and the NLRP3 inflammasome." (PMID 41394800, 2025). "Here we report evidence that electroacupuncture of mice at Neiguan acupoints can inhibit the up-regulation of cardiac HMGB1 following myocardial ischemia and attenuate the associated inflammatory responses and myocardial injury during reperfusion." (PMID 26499847, 2015). "Berberine upregulated miR-340-5p and suppressed inflammation in myocardial ischemia and inhibited HMGB1/TLR4/NF-κB signaling in cardiomyocyte apoptosis and cancer-related myocardial impairment." (PMID 40525842, 2025). "Patients with cerebral and myocardial ischemia have also been found to have elevated levels of HMGB1 in their blood serum, much in the same way MS patients have elevated blood serum levels of HMGB1." (PMID 35573828, 2022). "HMGB1 is up-regulated in a myocardial ischemia–reperfusion injury model, which increases the expression level of phosphorylated NF-κB p65, activates the NLRP3 inflammasome and induces the release of mature IL-1β." (PMID 35865525, 2022). "Certain DAMPs, such as high mobility group box 1 (HMGB1), have a detrimental role in acute myocardial ischemia and a beneficial effect in the post-ischemic myocardium." (PMID 35406729, 2022). "Klotho treatment significantly reduced the increase in the levels of circulating HMGB1 in blood at 4 h after myocardial ischemia." (PMID 35453645, 2022). "Previous studies have shown that HMGB1 regulates the PI3K/Akt/mTOR pathway in myocardial ischemia reperfusion injury and the ALI mouse model." (PMID 32636835, 2020). "HMGB1 release in the initial phase of myocardial ischemia is an early mediator of inflammation during myocardial I/R." (PMID 31344138, 2019). "At the early stage of myocardial ischemia, intracellular HMGB1, as well as other proteins, such as heat shock proteins and S100s (which are called damage associated molecular patterns, DAMPs), are passively released from necrotic cardiomyocytes." (PMID 31344138, 2019). "HMGB1 is a danger signal that senses cell damage especially in cardiac ischemia, and is an important candidate biomarker predicting the risk of cardiovascular events in clinic." (PMID 29681850, 2018). "This study showed that HMGB1-RAGE signaling pathway plays an important role in myocardial ischemia-reperfusion injury." (PMID 29789792, 2018). "Our study first confirmed that RIPostC can significantly inhibit myocardial local inflammatory responses by downregulation of RAGE/HMGB1 signaling pathways to alleviate myocardial ischemia-reperfusion injury." (PMID 29789792, 2018). "The cholinesterase inhibitor neostigmine mimicked the effects of electroacupuncture on HMGB1 release and myocardial ischemia reperfusion injury." (PMID 26499847, 2015). "High mobility group box 1 protein (HMGB1) has an important role in myocardial ischemia/reperfusion (I/R) injury." (PMID 24944626, 2014). "In patient studies with cerebral and myocardial ischemia, respectively, elevated levels of HMGB1 were seen within 24 hours." (PMID 25328284, 2014). "In conclusion this study contributes to our understanding of the role of HMGB1 in myocardial ischemia and reperfusion." (PMID 24371373, 2013). "C57BL/6 wild-type (WT) or TLR2−/−-mice were injected with vehicle, HMGB1, or HMGB1 BoxA one hour before myocardial ischemia (30 min) and reperfusion (24 hrs)." (PMID 24371373, 2013). "HMGB1 promoting IL‐17A release has been shown in myocardial ischemia–reperfusion injury." (PMID 38414294, 2024).
myocardial ischemia (continued). "In addition, it relieves myocardial ischemia/reperfusion injury by suppressing autophagy via the inhibition of HMGB1 (high mobility group box 1) by repressing KAT7 (lysine acetyltransferase 7) in MI." (PMID 36975887, 2023). "A critical role of HMGB1 in myocardial ischemia model is to induce tissue regeneration." (PMID 33287126, 2020). "Besides activating the NF-κB and MAPK pathways, recent studies also have demonstrated that HMGB1 regulates the PI3K/Akt/mTOR signaling pathway in myocardial ischemia/reperfusion injury and LPS-induced pulmonary inflammation in ALI models." (PMID 32636835, 2020). "Delivery of exogenous high mobility group box 1 (HMGB1) may exert a beneficial effect on myocardial ischemia–reperfusion (I/R) injury." (PMID 32063860, 2019). "The aim of the present study was to investigate whether postconditioning with simvastatin attenuated myocardial ischemia reperfusion injury by inhibiting the expression of high mobility group box 1 (HMGB1) in rat myocardium following acute myocardial ischemia." (PMID 25780404, 2015). "Besides the known involvement of its receptor RAGE, we here provide evidence for a role of TLR2 in mediating effects of endogenous HMGB1 released during acute myocardial ischemia and reperfusion." (PMID 24371373, 2013). "Studies have confirmed that HMGB1 interacts with RAGE to promote NF-κB activation and amplify the inflammatory response in myocardial ischemia-reperfusion injury." (PMID 35251212, 2022). "Two hours after myocardial ischemia reperfusion, the levels of RAGE and HMGB1 were significantly decreased in RIPostC group compared with those in I/R group." (PMID 29789792, 2018). "A prior study showed that when Toll-like receptor 4 was mutated or deficient, the rate of cardiomyocyte apoptosis and the infarct size decreased, with the expression of HMGB1 and TNF-α notably inhibited following myocardial ischemia/reperfusion." (PMID 25780404, 2015). "The results from the present study identify a relation between HMGB1 and TLR2-signalling in myocardial ischemia and reperfusion." (PMID 24371373, 2013). "Notably, berberine has been shown to inhibit the HMGB1/TLR4/NF-κB pathway in other inflammatory diseases, such as myocardial ischemia and neuroinflammation." (PMID 40525842, 2025). "Additionally, berberine inhibited HMGB1/TLR4 signaling, reducing pro-inflammatory cytokines and cardiomyocyte inflammation in myocardial ischemia." (PMID 40525842, 2025). "As an effective cholesterol modulator, rosuvastatin has been proven to regulate HMGB1 in cholestatic liver injury and myocardial ischemia, but its function in IDD has not yet been fully explored." (PMID 37222533, 2023). "The levels of HMGB1 and RAGE were higher at 24 hours of reperfusion than at 120 min of reperfusion, and the expression of P-Akt was gradually decreased at 24 hours after myocardial ischemia reperfusion." (PMID 29789792, 2018). "Moreover, HMGB1, another RBP, plays a role in myocardial ischemia–reperfusion injury by triggering cardiomyocyte apoptosis through the TLR4 axis, promoting the release of cytokines and mediation of the inflammatory response via HMGB1/TLR4-related pathways." (PMID 37858115, 2023).